FMO3 (flavin containing dimethylaniline monoxygenase 3)
Description:
Essential hepatic enzyme that catalyzes the oxygenation of a wide variety of nitrogen- and sulfur-containing compounds including drugs as well as dietary compounds. Plays an important role in the metabolism of trimethylamine (TMA), via the production of trimethylamine N-oxide (TMAO) metabolite. TMA is generated by the action of gut microbiota using dietary precursors such as choline, choline containing compounds, betaine or L-carnitine. By regulating TMAO concentration, FMO3 directly impacts both platelet responsiveness and rate of thrombus formation.
Synonyms: FMOII; TMAU; dJ127D3.1
Tractability: Antibody: UniProt predicts a signal peptide or a membrane-spanning region. PROTAC: its protein half-life has been measured.
Target class: Enzyme; Oxidoreductase
Safety:
Unwanted effects reported when the protein is acted on. In parentheses: how it was acted on, where the effect was seen, and who reports it.
cardiotoxicity (source: ClinPGx)
Gene: Protein-coding gene on chromosome 1 (171,085,113 to 171,118,675, forward strand). Ensembl gene ENSG00000007933.
Subcellular location: Microsome membrane; Endoplasmic reticulum membrane
Pathways (Reactome):
Disease: Defective FMO3 causes TMAU
Metabolism: FMO oxidises nucleophiles
Gene Ontology:
Molecular function: albendazole monooxygenase activity; hypotaurine monooxygenase activity; N,N-dimethylaniline monooxygenase activity; protein binding; trimethylamine monooxygenase activity; flavin adenine dinucleotide binding; NADP binding; oxidoreductase activity, acting on paired donors, with incorporation or reduction of molecular oxygen, NAD(P)H as one donor, and incorporation of one atom of oxygen
Biological process: taurine biosynthetic process
Cellular component: endoplasmic reticulum membrane
Genetic constraint (gnomAD): Loss-of-function variants: 34 observed, 34.45 expected, observed/expected ratio (o/e) 0.99, 90% interval 0.75 to 1.31. The upper end of that interval is the gene's LOEUF score, 1.31, which puts it in group 5 of 6, group 1 being the genes least tolerant of losing a copy. Missense variants: 626 observed, 640.51 expected, observed/expected ratio (o/e) 0.98, 90% interval 0.91 to 1.04. Synonymous variants: 208 observed, 231.35 expected, observed/expected ratio (o/e) 0.9, 90% interval 0.8 to 1.01.
Gene-disease validity (ClinGen):
ClinGen rates the evidence that FMO3 causes each of these diseases.
trimethylaminuria (autosomal recessive): Definitive. A rare inborn error of metabolism characterized by the presence of large amounts of trimethylamine in urine, sweat, and breath, resulting in a fishy body odor in affected individuals.
Homologues: Orthologues: chimpanzee FMO3 (99% identical), macaque FMO3 (94% identical), rabbit FMO3 (84% identical), dog FMO3 (83% identical), pig FMO3 (83% identical), guinea pig FMO3 (82% identical), rat Fmo3 (81% identical), mouse Fmo3 (80% identical), tropical clawed frog fmo3 (61% identical), Caenorhabditis elegans fmo-3 (39% identical), Caenorhabditis elegans fmo-5 (39% identical), Caenorhabditis elegans fmo-1 (38% identical), and 2 more. Paralogues in human: FMO2 (56% identical), FMO1 (54% identical), FMO5 (53% identical), FMO4 (52% identical), FOXRED2 (21% identical).
Diseases named in the same sentence as FMO3 in open-access papers:
FMO3 is named in the same sentence as 56 diseases in open-access papers, as found by Europe PMC text mining. Sharing a sentence is not in itself a finding about the gene and the disease. The quoted sentences say what the papers report.
atherosclerosis (22 papers, 2014 to 2025). A disease characterized by the build-up of fatty material and calcium deposition in the arterial wall resulting in partial or complete occlusion of the arterial lumen. "This study aimed to evaluate the effects of the spontaneous genetic mutation T329S in flavin-containing monooxygenase 3 (FMO3) on atherosclerosis (AS), fatty liver syndrome (FLS), and adiposity in 90-week-old layers." (PMID 35433899, 2022). "SNPs in or near Fmo3, Sele and Selp for Ath44, and Lbp and Pkig for Ath45 were suggested for further investigation as potential candidates underlying the atherosclerosis susceptibility." (PMID 24586312, 2014). "Previous studies have confirmed that FMO3 knockout can significantly reduce gut-microbiota-dependent TMAO-induced atherosclerosis and thrombosis, suggesting that therapies targeting FMO3 may reduce the ischemic stroke risk." (PMID 39595639, 2024). "Furthermore, knocking down FMO3 in liver-specific insulin receptor knockout mice prevented hyperlipidemia and atherosclerosis susceptibility concomitant with an increase in LDL receptors." (PMID 30347638, 2018). "The findings indicate that the suppression of FMO3 through the inhibition of FoxO1 can prevent blood fat, hyperglycemia, and atherosclerosis." (PMID 38321994, 2024). "FMO3, as the main source of TMA, intensively participates in the conversion of TMA into TMAO, and FMO3 deficiency results in low TMAO plasma concentration and represses atherosclerosis and tissue sterol metabolism." (PMID 34923910, 2022). "The knockdown of FMO3 using antisense oligonucleotide in mice has been shown to attenuate atherosclerosis." (PMID 27834801, 2016). "In any case, consistent with the prevention of hypercholesterolemia, FMO3 knockdown completely prevented the development of atherosclerosis in Paigen-fed LIRKO mice." (PMID 25849138, 2015). "Here the authors show that FMO3 is upregulated in various models of diabetes and link FMO3 with key transcriptional regulators of hepatic glucose and cholesterol synthesis, thus proposing a mechanistic connection between diabetes and atherosclerosis." (PMID 25849138, 2015). "Additionally, another recent study demonstrated that maternal hypercholesterolemia exacerbates the development of atherosclerosis with a positive association of aortic lesion size with both TMAO levels and increased FMO3 mRNA expression." (PMID 30347638, 2018). "Knocking down liver FMO3 in LDL receptor-deficient mice reduced the hepatic and plasma lipid levels, bile acid pool size, liver triglyceride secretion, ketone bodies and glucose and insulin levels, and prevented atherosclerosis." (PMID 30347638, 2018). "Knockdown of FMO3 in insulin-resistant mice suppresses FoxO1, a central node for metabolic control, and entirely prevents the development of hyperglycaemia, hyperlipidemia and atherosclerosis." (PMID 25849138, 2015). "Notably, the experimental suppression of FMO3 in insulin-resistant mice effectively inhibited FoxO1, a key metabolic regulatory node, and completely circumvented the progression of hyperglycemia, hyperlipidemia, and atherosclerosis." (PMID 40395816, 2025). "We also asked whether knockdown of FMO3 could prevent atherosclerosis in LIRKO mice." (PMID 25849138, 2015). "Although this may not be the causal SNP for atherosclerosis, these results suggest a possible mechanism for altered Fmo3 expression." (PMID 24586312, 2014). "High blood sugar levels can trigger the overexpression of FMO3, an enzyme involved in the TMAO pathway, which can lead to increased TMAO levels and worsen atherosclerosis." (PMID 39092284, 2024). "By contrast, FMO3 knockdown mice had decreased circulating TMAO levels and attenuated atherosclerosis plaque formation." (PMID 34294762, 2021).
atherosclerosis (continued). "The knockdown of FMO3 not only resulted in decreased TMAO levels but also regulated both lipid metabolism and inflammation, thereby attenuating atherosclerosis." (PMID 27834801, 2016). "FMO3 knockout mice and subjects with a genetic defect in FMO3, despite having higher levels of TMA, are not characterized by a higher risk of atherosclerosis." (PMID 34360538, 2021). "In addition, knockdown of FMO3, resulting in the absence of TMAO, can prevent the development of hyperglycemia and atherosclerosis in a diabetes mouse model, suggesting that the FMO3/TMAO pathway may play an important role in the pathophysiology of diabetes." (PMID 26676906, 2016).
trimethylaminuria (21 papers, 2005 to 2025). "Mutations in FMO3 cause trimethylaminuria, also known as “fish odor syndrome”, a condition in which a defective FMO3 enzyme causes accumulation of trimethylamine, which results in a distinctive odor resembling rotten fish." (PMID 40892834, 2025). "It is interesting to note that bacterially derived TMA smells like rotting fish, and humans with mutations in the TMA to TMAO converting enzyme FMO3 have a disease known as “fish odor syndrome” or TMA." (PMID 37777156, 2023). "Genetic deficiency in FMO3 is reported to predispose to fish odor syndrome, a rare condition resulting from the failure to convert TMA to TMAO." (PMID 37834065, 2023). "We realized an experimental study to investigate the role of several coding variants carried by the FMO3 gene in a cohort of patients affected by trimethylaminuria." (PMID 34834137, 2021). "In the meantime, the role of many polymorphic variants able to impact on FMO3 folding and activity is still unexplored, as well as the involvement of haplotypes in the onset and progression of trimethylaminuria." (PMID 34834137, 2021). "The mutation deficiency of FMO3 results in a rare disease named trimethylaminuria, which is characterized by the failure to break down TMA." (PMID 32108960, 2020). "The aim of this study was to screen another self-reported Japanese trimethylaminuria cohort for novel FMO3 variants and to investigate these new variants." (PMID 28649550, 2015). "Polymorphic human flavin-containing monooxygenase 3 (FMO3, EC 1.14.13.8) is associated with the inherited disorder trimethylaminuria — the inability to metabolize odorous dietary-derived trimethylamine to its non-odorous N-oxide." (PMID 28649550, 2015). "Currently, Japanese subjects(from different families) with trimethylaminuria are known to possess p.(Cys197Ter), p.(Arg205Cys), and p.(Arg500Ter) FMO3 alleles with frequencies in the range of 2–4%." (PMID 28649550, 2015). "The duplicated regions harbor a total of five protein-coding genes: MROH9 and members of the flavin-containing monooxygenase family, including FMO3 (mutations cause the recessive disorder Trimethylaminuria; MIM 602079), FMO2, FMO1, and FMO4, all located within the chr1_D region." (PMID 39257002, 2024). "Notably, patients with loss-of-function mutations in FMO3 often suffer from trimethylaminuria (fish odor syndrome)." (PMID 33083493, 2020). "The most studied FMO is the human Fmo3, an enzyme that is constitutively active in the adult human liver where it participates in the oxidation of drugs and xenobiotics, and mutations in Fmo3 contribute to the disease trimethylaminuria." (PMID 32812865, 2020). "In the current study, six novel FMO3 variants with impaired trimethylamine and benzydamine N-oxygenation capacity were discovered in a Japanese population with self-reported trimethylaminuria; these variants are likely causative of trimethylaminuria." (PMID 28649550, 2015). "Mutations in the FMO3 gene have been found to contribute to the disease trimethylaminuria (TMAuria), an inborn error of metabolism resulting from diminished oxidation of the tertiary amine trimethylamine to trimethylamine N-oxide resulting in a severe body odour in affected individuals." (PMID 25243081, 2014). "We and others have shown that recessivity for mutations of FMO3 cause TMAuria." (PMID 16324215, 2005). "Females with moderate to severe TMAuria note exacerbations perimenstrually and it is proposed that decreases in FMO3 enzymatic activity resulting from polymorphisms could also be influenced by hormonal events." (PMID 16324215, 2005). "The observation that a number of patients with TMAuria are hypertensive was the basis to the hypothesis that there may be an association between variants in the FMO3 gene and hypertension." (PMID 16324215, 2005). "Primary trimethylaminuria (TMAU) is characterized by systemic accumulation of trimethylamine (TMA) due to the deficient activity of flavin‐containing monooxygenase 3 (FMO3)." (PMID 40078825, 2025).
trimethylaminuria (continued). "Subjects with genetic mutations in the FMO3 gene exhibit abnormally high TMA levels due to reduced conversion to TMAO, clinically manifesting as trimethylaminuria (fish-odor syndrome)." (PMID 41155754, 2025). "In trimethylaminuria (TMAu or “fish odor syndrome”) TMA is accumulated and excreted to the body fluids, because of deficiency of flavin-containing monooxygenase 3 (FMO3), a liver enzyme oxidizing TMA." (PMID 32326126, 2020). "More than 300 single nucleotide polymorphisms of the human FMO3 have been reported and over 40 of these polymorphisms have been linked to trimethylaminuria (TMAU) also known as “fish odor syndrome”." (PMID 25288227, 2014). "Loss-of-function mutations in FMO3 gene can result in defective TMA N-oxygenation, giving rise to disorder known as “fish-odour syndrome” in human, as well as the fishy off-flavor in cow milk and chicken eggs." (PMID 24282592, 2013). "While FMO3 inhibitors reduce TMAO levels, they risk adverse effects like hepatic inflammation, and individuals with FMO3 gene defects may develop trimethylaminuria (fish odour syndrome)." (PMID 40777990, 2025). "In our 2012 report, we screened and investigated 640 Japanese volunteers with self-reported trimethylaminuria; in this current study, we screened and investigated novel FMO3 variants in a further 171 Japanese volunteers with self-reported trimethylaminuria." (PMID 28649550, 2015). "The FMO3 gene is highly polymorphic, with genetic variations in both coding and non-coding regions that can influence enzyme functionality and contribute to the observed phenotypic spectrum in trimethylaminuria, with symptoms ranging from mild and transient to more severe forms." (PMID 40125190, 2025). "Finally, hepatic FMO3 is the primary FMO responsible for trimethylamine N-oxide (TMAO) production from trimethylamine, so that genetic mutations affecting the production or activity of FMO3 result in the disorder trimethylaminuria (or fish-odour syndrome)." (PMID 39636438, 2024). "FMO3 is a significant enzyme in the liver that can convert TMA into TMAO, whereas the inhibition of FMO3 leads to accumulation of TMA, which induces trimethylaminuria, also known as fish malodor syndrome." (PMID 32108960, 2020). "Trimethylaminuria (TMAU) is a genetic disorder whereby people cannot convert trimethylamine (TMA) to its oxidized form (TMAO), a process that requires the liver enzyme FMO3." (PMID 28196478, 2017).
Obesity (15 papers, 2018 to 2025). Accumulation of substantial excess body fat. "The association between circulating TMAO levels and obesity is critically dependent on the expression and activity of host hepatic and adipose flavin monooxygenase 3 (FMO3)." (PMID 41488302, 2025). "FMO3 deficiency confers protection against TMAO-induced obesity and modulation of energy metabolism." (PMID 36394956, 2023). "Further studies found that mice with FMO3 deletion were protected from obesity caused by a high‐fat diet." (PMID 35285096, 2022). "It was suggested that higher activity of the enzyme FMO3, which metabolizes TMA to TMAO, might cause the observed increase, since FMO3 is known to be upregulated in obese patients, and PsA, as well as Ps, is linked to obesity and metabolic syndrome." (PMID 35743709, 2022). "In addition, high expression of FMO3 is also associated with obesity, and FMO3 knockdown or genetic deletion showed a higher positivity of UCP1 in WAT." (PMID 31262098, 2019). "Schugar and her colleagues discovered that FMO3 mRNA expression in men is positively correlated with obesity, and FMO3 knockout protects mice against high-fat-diet-induced obesity." (PMID 35202247, 2022). "Further, antisense oligonucleotide-mediated knockdown, or genetic deletion of the TMAO-producing enzyme, flavin-containing monooxygenase 3 (FMO3), offers protection against hyperglycemia, hepatic insulin resistance, and obesity in mice." (PMID 32903435, 2020). "The causal role of FMO3 is supported by interventional studies, whether TMAO itself is an independent pathogenic driver or a biomarker in human obesity requires further clarification." (PMID 41488302, 2025). "Furthermore, genetic deletion/knockdown of FMO3 stimulated beiging of white adipose tissue and conferred protection against obesity in mice." (PMID 36310589, 2022). "Possible underlying mechanisms might involve the role of TMAO-producing enzyme (i.e., flavin-containing monooxygenase-3 (FMO3)) in regulating obesity and beiging of white adipose tissue, as well as increased hepatic insulin resistance correlate with elevated TMAO concentration." (PMID 41291687, 2025). "Furthermore, the expression of FMO3 in subcutaneous white adipose tissue was found to be positively associated with obesity in mice and humans, and FMO3 was identified as a negative regulator of the beiging of white adipose tissue." (PMID 36310589, 2022). "In contrast, the casein-fed groups showed a significantly higher hepatic FMO-3 abundance, and the addition of fat in the diet further increased FMO-3, % body fat, and high insulin levels, which have been associated with increased production of TMAO, obesity and insulin resistance." (PMID 32340138, 2020). "Flavin-containing monooxygenase 3 (FMO3), the enzyme responsible for TMAO production is involved in obesity and the beginning of white adipose tissue." (PMID 39328991, 2024). "Finally, the groups fed BB showed lower abundance of hepatic FMO-3, even with a high-fat diet protecting against the production of TMAO and obesity." (PMID 32340138, 2020). "Moreover, other studies have shown that FMO3 expression (the enzyme that converts TMA into TMAO) is closely related to fat adipose tissue and its inhibition converts WAT adipocytes to “brown-like” adipocytes known as beige cells that promote protection against obesity." (PMID 38139384, 2023).
Hyperglycemia (12 papers, 2015 to 2025). An increased concentration of glucose in the blood. "Others have demonstrated that knockdown of flavin containing monooxygenase 3 (FMO3)–which produces TMAO–in insulin resistant mice blocks the development of hyperglycemia." (PMID 31940332, 2020). "Thus, in ob/ob mice, as in LIRKO mice, the knockdown of FMO3 can activate SREBP-2/miR-182 and suppress FoxO1 and hyperglycaemia." (PMID 25849138, 2015). "Furthermore, manipulation of gut microbiota or knockdown of FMO3 in insulin-resistant mice inhibited TMAO production, reduced PERK activation and suppressed FoxO1 in the liver, which may prevent the development of hyperglycemia." (PMID 35982495, 2022).
Insulin resistance (11 papers, 2015 to 2025). Increased resistance towards insulin, that is, diminished effectiveness of insulin in reducing blood glucose levels. "Taken together, these data indicate that FMO3 expression, which is directly inhibited by insulin and induced by glucagon and corticosteroids, is increased in male mice with insulin deficiency/insulin resistance." (PMID 25849138, 2015). "Together, these results showed that Fmo3 knockdown improved both β-cell function and insulin resistance in db/db mice." (PMID 38514666, 2024). "Knockdown or inhibition of Fmo3, the TMAO-producing enzyme, prevented insulin resistance in liver insulin receptor knockout (LIRKO) mice and inhibited obesity in HFD-fed mice." (PMID 38514666, 2024). "Inhibition of TMAO synthesizing enzyme, flavin-containing monooxygenase 3 (FMO3), with 3,30 -diindolylmethane reduces PERK Activation and Insulin resistance in vivo suggesting a potential route of the therapeutic intervention for metabolic syndrome." (PMID 33525374, 2021).